TREM2 (triggering receptor expressed on myeloid cells 2)
Diseases named in the same sentence as TREM2 in open-access papers (continued):
Sharing a sentence is not in itself a finding about the gene and the disease.
neurodegenerative disease (continued). "Recently, RNAseq data suggested APOE in combination with TREM2 to induce the microglial phenotypic changes observed in neurodegenerative diseases." (PMID 30459560, 2018). "At the same time, it was reported that TREM2-APOE pathway drives transcriptional phenotype of dysfunctional microglia in neurodegenerative diseases." (PMID 30618585, 2018). "Deranged synaptic and immune function have been reported in HD, and concentrations of the synaptic protein neurogranin and the microglial protein TREM2 are increased in other neurodegenerative diseases." (PMID 29523800, 2018). "This novel study provides many answers regarding the relationship between TREM2 and ApoE in neurodegenerative diseases." (PMID 30572908, 2018). "A new study has shed light on the function of the TREM2/ApoE connection in neurodegenerative diseases including AD." (PMID 30572908, 2018). "TREM2 modulates phagocytosis, decreases microglial inflammation, and plays a role in neurodegenerative diseases." (PMID 28588439, 2017). "Mutations in various phagocytosis genes (TREM2, complement receptor 1, CD33, APOE, etc.)were also implicated as risk factors for neurodegenerative diseases." (PMID 28340576, 2017). "Knowing that the TREM2/ApoE interaction is presumably relevant to AD pathogenesis and perhaps also to other neurodegenerative diseases, we found it essential to determine the extent to which human ApoE stimulated murine TREM2 signaling." (PMID 28320424, 2017). "Despite this abundance of genetic validation, the pathways linking TREM2 to neurodegenerative disease have yet to be identified and strategies for therapeutic modulation are not evident." (PMID 29037207, 2017). "This suggests a significant role for TREM2 in neurodegenerative diseases with phenotypes being dependent upon the location of the mutation and the severity of protein dysfunction." (PMID 28320424, 2017). "In addition to its role in AD, TREM2 modulates microglial activity in other neurodegenerative diseases, including PD and ALS." (PMID 41292555, 2025). "Conversely, one study proposes that suppressing TREM2 activation in neurodegenerative disease may be protective, since TREM2 signaling through the TREM2–Apolipoprotein E (ApoE) axis drives microglia toward the MGnD phenotype and promotes neuronal loss." (PMID 41465422, 2025). "Gaining deeper insight into TREM2 functions is critical and may offer promising avenues for research on neurodegenerative diseases." (PMID 40806186, 2025). "TREM2 is a microglia-specific type I transmembrane receptor that plays a crucial role in regulating microglial activity, particularly in synaptic pruning and the pathophysiology of neurodegenerative diseases." (PMID 41292555, 2025). "One example is VGL101 (NCT05677659), also known as iluzanebart, a fully human TREM2 monoclonal antibody agonist used to treat adult-onset leukoencephalopathy with axonal spheroids and pigmented glia (ALSP), a rare and fatal neurodegenerative disease caused by mutations in the CSF1R gene." (PMID 40242752, 2025). "Although our findings support the role of TREM2 in improving mitochondrial dysfunction for the treatment of neurodegenerative diseases and neuroinflammation, this study has limitations because of its in vitro nature, and cannot fully represent the actual situation in vivo." (PMID 39997067, 2025). "In recent years, with in-depth studies of neurodegenerative diseases, especially Alzheimer’s disease (AD), the prominent role of the Trem2 gene has become increasingly apparent, including its functions in suppressing neuroinflammation and regulating metabolism." (PMID 39997067, 2025). "Subsequent studies established the role of TREM2 in neurodegenerative diseases." (PMID 41476737, 2025).
neurodegenerative disease (continued). "Modulation of TREM2 impacts the regulatory kinase GSK-3β, which has a distinct role in the pathogenesis of various neurodegenerative diseases, and is associated with the PI3K–AKT–GSK-3β–mTOR signaling axis, a critical pathway for cellular metabolism, growth, and proliferation." (PMID 41465422, 2025). "Therefore, Trem2 becomes a crucial target for investigating the pathological mechanisms of neurodegenerative diseases and exploring novel therapeutic strategies." (PMID 40205810, 2025). "By selectively targeting the TREM2 pathway based on its interaction with specific HS structures, we may unlock novel treatment avenues for AD and other neurodegenerative diseases." (PMID 39159814, 2024). "In addition, Trem2, as a significant receptor for Apoe, has been a focal point in the field of neurodegenerative disease research." (PMID 39272194, 2024). "DAM in AD must be intrinsically different than in other neurodegenerative diseases, as TREM2 is not a major player or risk factor." (PMID 39564189, 2024). "TREM2 is involved in immunomodulatory processes and neurodegenerative diseases." (PMID 38393046, 2024). "The TREM2-ApoE pathway is crucial for regulating microglial activity in neurodegenerative diseases and may help restore homeostatic microglia." (PMID 39744521, 2024). "Growing evidence suggests that TREM2 plays a beneficial role in neurodegenerative diseases." (PMID 37013543, 2023). "A stage-specific deletion of the TREM2 gene may be important for the analysis of the precise functions of the DAM in neurodegenerative diseases." (PMID 37369603, 2023). "In addition to promoting anti-inflammatory effects, TREM2 enhances the phagocytic capacity of microglia and plays a role in a variety of neurodegenerative diseases, such as AD, PD, and MS." (PMID 36672106, 2023). "Many studies in the field of neurodegenerative diseases have explored the vital role of TREM2." (PMID 36672106, 2023). "Besides activating TREM2 using agonistic antibodies, improving the level of TREM2 is also a promising method for attenuating neurodegenerative disease." (PMID 37433768, 2023). "Thus, it is becoming clear that TREM2 is a major player at the intersection of cancer, metabolic, and neurodegenerative diseases." (PMID 36627355, 2023). "Interestingly, recent data point to the association between TREM2 expression and the appearance of a specific microglial type (“disease-associated microglia”, DAM), with a characteristic molecular signature, in neurodegenerative diseases including AD." (PMID 34587978, 2021). "TREM2 plays an active role in the pathogenesis of various neurodegenerative diseases (NDDs)." (PMID 34895041, 2021). "This latter finding may be crucial in interpreting the results obtained by using mouse microglia in the context of neurodegenerative diseases involving TREM2." (PMID 33093587, 2020). "The signature found in this study includes both factors reported to be beneficial in the context of ALS (Igf1, Grn, Trem2, Tyrobp, etc.), and factors known to be detrimental (Mmp12, Optn, Cybb, etc.), as well as some like Spp1, Gpnmb, and Itgax recurrently found in neurodegenerative diseases." (PMID 32318054, 2020). "Recently, the term neurodegeneration-associated molecular pattern (NAMPs) has been suggested, which includes an array of danger signals commonly present in different neurodegenerative diseases and recognized by different receptors (including TREM2) to switch from homeostatic microglia to DAM." (PMID 31627485, 2019). "Much attention is currently being given to TREM2 in AD and other neurodegenerative diseases." (PMID 31426806, 2019). "Interestingly, a rare mutation on the triggering receptor expressed on myeloid cells 2 (TREM2), a gene that facilitates microglial phagocytosis, increases the risks of neurodegenerative diseases, including AD." (PMID 30149799, 2018).
neurodegenerative disease (continued). "Further work investigating the mechanisms of how TREM2 influences the reaction of microglia to neuronal injury may shed light on the microglial dysfunction in neurodegenerative diseases and identify suitable drug targets for future treatments." (PMID 30157425, 2018). "Indeed, the TREM2-apoE pathway has been identified as a major regulator of microglia phenotypic change in neurodegenerative diseases." (PMID 30532704, 2018). "In addition, risk genes for neurodegenerative diseases, such as APOE and TREM2 are enriched in purified adult human microglia." (PMID 30108586, 2018). "TREM2, which is expressed at high levels in microglia, plays a role in neurodegenerative diseases." (PMID 28588439, 2017). "Higher levels of TREM2 mRNA might reflect the activation of microglial cells in the AD-affected brain, a phenomenon well known to occur in neurodegenerative diseases." (PMID 27051467, 2016). "Together, these findings indicate that TREM2 may be a common denominator in the pathogenesis of several different neurodegenerative diseases." (PMID 26941262, 2016). "Once this relationship has been established, subsequent experiments should investigate the phenotype of TREM2-R47H-expressing microglia under conditions that mimic early steps in the neurodegenerative disease process (e.g., Aβ accumulation and amyloid plaque deposition in AD)." (PMID 26337043, 2015). "Together these studies unequivocally implicated TREM2 p.R47H in AD risk; however its role in other neurodegenerative diseases has not yet been studied." (PMID 23800361, 2013). "Furthermore, we highlight a critical regulatory role of TREM2 in the interferon pathway, thereby providing a new perspective on the anti-inflammatory effects of TREM2 and offering novel ideas for developing interventions for neurodegenerative diseases." (PMID 38956653, 2024). "The TREM2–AD relation could be of importance in the search for novel therapeutic strategies for the medical therapy of AD and other neurodegenerative diseases, for which current therapies merely provide relief to acute symptoms, while brain neurodegeneration proceeds exponentially." (PMID 37513845, 2023). "However further work is needed to understand the exact molecular mechanisms by which R47H TREM2 gains function and how this may contribute to neurodegenerative disease." (PMID 36480007, 2023). "Although TREM2 has been closely implicated in the pathogenesis of neurodegenerative diseases, it has not been fully determined whether TREM2 exhibits a protective or detrimental role in the development and progression of the diseases." (PMID 35592778, 2022). "TREM2 is one of the major receptors of ApoE, the interactions between ApoE and TREM2 are important in the context of AD pathogenesis, and the TREM2–ApoE pathway has been reported to be a major regulator of the microglial functional phenotype in neurodegenerative diseases." (PMID 35582645, 2022). "In neurodegenerative diseases, a specific type of microglia was found, subsequently classified as disease-associated microglia (DAM) characterized by transcriptional changes driven by apolipoprotein E (APOE) and the triggering receptor expressed on myeloid cells 2 (TREM2)." (PMID 34054862, 2021). "In studies of these neurodegenerative diseases, which should be closely related to neuroinflammation, it has been demonstrated that TREM2 is involved in regulating the activation of microglia, which indicates that TREM2 improve disease progression through the regulation of neuroinflammation." (PMID 34867158, 2021). "Moreover, it has been demonstrated that overexpression of TREM2 could suppress inflammatory response in animal models of Alzheimer disease, Parkinson disease, multiple sclerosis, and other neurodegenerative diseases." (PMID 32466767, 2020).
neurodegenerative disease (continued). "The variant structures investigated in this study provide a good starting point for examining the role of TREM2 structure in the binding of physiologic and pathologic ligands and may be directly useful in efforts toward rational drug design targeting TREM2 in other neurodegenerative diseases." (PMID 32021611, 2019). "Although the functional consequences of the variant remain to be established, such findings pave the way to inquire alternative disease risk mechanisms and may, therefore, promote our understanding of the role of TREM2 in AD and other neurodegenerative diseases." (PMID 30917570, 2019). "A TREM2/DAP12-targeted strategy could provide new therapies for neurodegenerative diseases." (PMID 30127720, 2018). "Our study is the first to show an increase in TREM2+ cells in response to a western diet suggesting TREM2 could be a critical molecule in modulating microglia/monocyte activation in response to dietary factors as well as in neurodegenerative diseases." (PMID 26888450, 2016). "Jonathan Kipnis and others highlight the role of the TREM2-APOE pathway in driving microglial dysfunction in AD and other neurodegenerative diseases." (PMID 40791247, 2025). "Other significantly downregulated genes included TREM2 and LPL, both highly expressed in microglia, and known to be involved in neurodegenerative diseases like AD through their function in regulating microglia lipid homeostasis as well as immune function." (PMID 41333389, 2025). "Triggering receptor expressed on myeloid cells 2 (TREM2) is an immunomodulatory receptor enriched in microglia and tissue macrophages, known to play protective roles in retinal and neurodegenerative diseases." (PMID 40716081, 2025). "These pathways were, in general, shared across all neurodegenerative diseases, even though the major overlap was found for the synaptic functions (BDNF, CCL2, ACHE, GFAP, NEFH or NEFL) and microglia pathways (TREM2, IL13, IL6R IFNG)." (PMID 41250190, 2025). "Trem2 is a key molecule regulating the transition of microglia to the DAM state, playing a vital role in various neurodegenerative diseases." (PMID 41574049, 2025). "Studies have shown that TREM2 function is closely related to APP processing pathways and downstream pathways in neurodegenerative diseases." (PMID 40806186, 2025). "Likewise, the upregulation of Trem2 and Apoe, key regulators of microglial activation, suggests that TREM2-targeted therapies, which have shown promise in neurodegenerative disease models, may hold therapeutic potential for mitigating neuroinflammatory damage in aging." (PMID 40563967, 2025). "In this context, selectively promoting TREM2‐mediated lipid metabolism and polarization of microglia into M2‐like phenotype could be an effective way to prevent sevoflurane‐induced developmental neurotoxicity and neurodegenerative diseases, although the mechanism remains unclear." (PMID 38145349, 2024). "The TREM2-APOE signature not only characterizes the functional and transcriptional state of microglia but also plays a crucial role in the progression of neurodegenerative diseases, making it a potential target for targeted therapeutic interventions." (PMID 39456734, 2024). "The TREM2-APOE relationship can be considered a microglia-specific signature, especially in the context of neurodegenerative diseases." (PMID 39456734, 2024). "In particular, mounting evidence from AD patients and experimental models indicates pivotal roles for TREM2, CD33, and CD22 in neurodegenerative disease progression." (PMID 37276426, 2023). "This study discusses how ROS interacts with microglia in the striatum of patients with advanced neurodegenerative diseases based on the region-specific alteration in levels of microglial neurobiological phenotypes: MPO, PAR, and TREM2." (PMID 32842621, 2020).
neurodegenerative disease (continued). "Moreover, a specific microglia phenotype has been described in neurodegenerative diseases characterized by the downregulation of microglia homeostatic genes, the upregulation of specific degeneration associated markers (DAM), and sustained by the upregulation of TREM2." (PMID 31551688, 2019). "Uncovering the molecular pathways activated by TREM2 during microglia activation under disease conditions and how this microglia polarization may lead to harmful oxidative stress will help to develop novel therapeutic approaches to treat neurodegenerative diseases." (PMID 31627485, 2019). "This work identifies the TREM2-APOE axis as a master regulator of the microglial functional phenotype in aging and neurodegenerative diseases, inducing a microglia phenotypic switch from a homeostatic to a neurodegenerative phenotype." (PMID 29361745, 2018). "Expression of human TREM2 R47H in Trem2 knockout mice failed to rescue the knockout phenotypes again supporting the notion that TREM2 is protective and that TREM2 variants associated with neurodegenerative diseases may cause a loss-of-function." (PMID 30185230, 2018). "Our results implied that the body may initiate endogenous mechanisms akin to those involved in neurodegenerative diseases through early remyelination after TBI, partially regulated by TREM2." (PMID 38649789, 2024). "TREM2 activation by APOE induces significant changes in microglia gene expression and in models of neurodegenerative diseases, such as APP-PS1 mice (a model for AD); the activation of this signaling pathway is associated with increased amyloid plaque pathology." (PMID 39456734, 2024). "Within other pathological neurodegenerative disease-states like PD, where APOE and TREM2 do not appear to be implicated in disease risk or pathogenesis, it is likely that other implicated genes drive an analogous development of a functionally similar DAM." (PMID 39564189, 2024). "Other potential AD plasma biomarkers could be related to abnormal astroglia activation response in neurodegenerative diseases (e.g., GFAP), triggering receptor expressed on myeloid cells 2 (TREM2))." (PMID 36674742, 2023). "For this reason, some authors suggest that manipulating the TREM2-APOE pathway could be a potential therapeutic approach to restore the homeostatic state of microglia and possibly treat neurodegenerative diseases." (PMID 38132144, 2023). "The answers could help develop TREM2- and CD14-targeted therapy to treat AD and related neurodegenerative diseases." (PMID 37483607, 2023). "Notably, the TREM2-APOE pathway has been identified as a major regulator of dysfunctional microglia and as a therapeutic target for neurodegenerative diseases." (PMID 36091018, 2022). "Triggering receptors expressed on myeloid cells 2 (TREM2), phosphoinositide-specific phospholipase C (PLC) γ2, and protein kinase C (PKC) promote the activation of reparative/regenerative microglial subtypes which are beneficial for neurodegenerative diseases." (PMID 35722618, 2022). "Triggering receptors expressed on myeloid cells 2 (TREM2) is a broadly expressed PRR on macrophages, dendritic cells, and microglia cells, which be considered an important therapeutic target for neurodegenerative disease, infectious disease and tumor immunotherapy." (PMID 36068223, 2022). "Fourth, microglial activation in neurodegenerative diseases is highly complex and requires an interplay of multiple signaling pathways besides TREM2, which were not assessed in the current study." (PMID 33032659, 2020). "However, TREM2/DAP12 have also been shown to control microglial activity and consequently affect the fate of damaged neurons after neuronal injury and in neurodegenerative diseases besides AD." (PMID 30127720, 2018).